MIR6775 (microRNA 6775)
Synonyms: hsa-mir-6775
Gene: MicroRNA gene on chromosome 16 (87,834,592 to 87,834,660, reverse strand). Ensembl gene ENSG00000278598.
Homologues: Orthologues: chimpanzee MIR6775 (100% identical).